TGFBR2 (transforming growth factor beta receptor 2)
Diseases named in the same sentence as TGFBR2 in open-access papers (continued):
Sharing a sentence is not in itself a finding about the gene and the disease.
diabetes (5 papers, 2017 to 2025). "The purpose of this study is to investigate the associations of nine single nucleotide polymorphisms (SNPs) at TGFBR2 and three SNPs at TGFBRAP1 with T2DM and to evaluate its genetic effects on diabetes‐related miRNA expression." (PMID 30461200, 2019). "A case‐control was conducted to evaluate the associations of the polymorphisms of TGF‐β1 receptor‐associated protein 1 (TGFBRAP1) and TGF‐β1 receptor 2 (TGFBR2) with type 2 diabetes mellitus (T2DM), and its genetic effects on diabetes‐related miRNA expression." (PMID 30461200, 2019). "Thus, we further removed control subjects with a self-reported diagnosis of hyperlipidemia, hypertension or diabetes and then investigated the association between MetS and two key SNPs, namely SMAD2 rs11082639 and TGFBR2 rs3773651." (PMID 29051557, 2017). "Therefore, Tgfbr2 deletion in the bone marrow mirrors diabetes-induced changes such that reduced expression of the TGFB pathway, including the downstream mediators, may remove the suppression and allow bm-MPCs to readily differentiate into adipocytes." (PMID 36307522, 2022).
keloid (5 papers, 2016 to 2024). An irregularly shaped, elevated mark on the skin caused by deposits of excessive amounts of collagen during wound healing. "To demonstrate an association between TEM1 and TGFBR2 in vivo, we used double immunofluorescence staining in keloids and normal skins." (PMID 38254097, 2024). "ScRNA-seq analysis identified consistent expression patterns for TEM1, ACTA2, COL1A1, FN1, TGFBR1, and TGFBR2 in distinct fibroblast subsets of both keloids and hypertrophic scars." (PMID 38254097, 2024). "Higher expression levels of TEM1 and TGFBR2 were detected in keloids than in normal skin; TEM1 expression correlated positively with TGFBR2 (r2 = 0.6947)." (PMID 38254097, 2024). "TEM1 was found to be highly co-localized with TGFBR2 in dermal tissues from keloids and normal skin." (PMID 38254097, 2024). "In addition, the mRNA expression levels of ECM genes including COL1A1 and FN1 as well as that of TGF-β-related genes such as TGFB1, TGFBR1, and TGFBR2 were highly expressed in keloids." (PMID 38254097, 2024). "In the skin, TGFBR2 expression is increased in SSc fibroblasts as well as in keloids." (PMID 27274768, 2016).
Myocardial fibrosis (5 papers, 2022 to 2025). "For instance, in a mouse model of cMyBP-C cardiomyopathy, both cardiomyocyte hypertrophy and myocardial fibrosis could be prevented or attenuated by deleting a key TGF-β receptor (Tgfbr2) in myofibroblasts." (PMID 37443910, 2023). "MiR-671 in ASC-derived exosomes targeted the transforming growth factor beta receptor 2 (TGFBR2) and suppressed the phosphorylation of SMAD2, enhancing cardiomyocyte viability and reducing myocardial fibrosis and inflammation." (PMID 38132104, 2023).
type 2 Marfan syndrome (5 papers, 2012 to 2025). "The identified pathways from these analysis suggest that some patients suffered from Marfan syndrome type 2, which is based on mutations in the TGFBR2 gene (associated pathway “Loss of Function of TGFBR2”)." (PMID 31918677, 2020).
endometrial cancer (4 papers, 2018 to 2022). Primary or metastatic malignant neoplasm involving the endometrium (mucous membrane that lines the endometrial cavity). "From Cancer Cell Line Encyclopedia (Novartis/Broad, Nature 2012), inactivating frameshift mutations of TGFBR2 can be detected in endometrial cancer cell lines, such as COLO684, HEC59, HEC108, HEC151, HEC265, JHUEM1, JHUEM2, and RL95-2." (PMID 30510261, 2018). "The HNPCC patients display TGFBR2 mutations more frequently in colorectal than endometrial cancers (88% vs. 25%), and the main difference between these tumor types is PTEN instability, which seems to be characteristic for uterine tumorigenesis in this pathology." (PMID 34501347, 2021). "This suggests that the loss of function of TGFBR2 confers a survival advantage for cancer cells during tumorigenesis for MSI-H CRCs, but this is less evident in MSI-H endometrial cancers." (PMID 36531239, 2022). "For instance, TGF-β receptor 2 (TGFBR2) was the first MSI gene to be identified, and several frameshift mutations leading to loss of function in this gene are seen in 80% of MSI-H CRCs, while less commonly so in endometrial cancers." (PMID 36531239, 2022). "Since TGFBR2 is partially silencing mutated in Ishikawa and Ishikawa-02 cells, instead of adopting short-term TGF-β treatment for 24 hours used in the conventional invasion assay, we measured long-term TGF-β effect for 10 days on endometrial cancer cell growth and SOX2 expression." (PMID 30510261, 2018).
head and neck squamous cell carcinoma (4 papers, 2012 to 2024). A squamous cell carcinoma that arises from any of the following anatomic sites: lip and oral cavity, nasal cavity, paranasal sinuses, pharynx, larynx, and salivary glands. "TGFBR2 is recurrently mutated in OL as well as in head and neck squamous cell carcinoma (HNSCC)." (PMID 27294413, 2016).
leiomyoma (4 papers, 2013 to 2022). A well-circumscribed benign smooth muscle neoplasm characterized by the presence of spindle cells with cigar-shaped nuclei, interlacing fascicles, and a whorled pattern. "The mean expression levels of miR-181a-5p, 127-3p, 28-3p, 30b-5p and let-7c-5p were higher in patients with IGF2BP1 and TGFBR2-positive leiomyoma." (PMID 35639702, 2022). "TGFBR2 was more frequently positive in patients with ≥ 6 cm leiomyoma and mass effect." (PMID 35639702, 2022). "Particularly, the five miRs including miR-181a-5p, 127-3p, 28-3p, 30b-5p and let-7c-5p, and their target molecules including TGFBR2 and IGF2BP1, were up-regulated in leiomyoma tissues." (PMID 35639702, 2022). "The mean expression levels of miR-181a-5p, 127-3p, 28-3p, 30b-5p and let-7c-5p were higher in cases with TGFBR2 and IGF2BP1 positive leiomyoma." (PMID 35639702, 2022). "Therefore, we strongly suspected that such changes in miR up-regulated TGFBR2 and IGF2BP1 in leiomyoma tissue and affected its growth." (PMID 35639702, 2022). "In this vein, asoprisnil, a steroidal 11β-benzaldoxime-substituted selective progesterone receptor modulator (SPRM), targets TGFB3 and TGFBR2 in leiomyoma cells but not normal myometrial cells, providing a potentially effective treatment option for leiomyoma." (PMID 25478164, 2014). "Leiomyoma tissues but not the adjacent myometrium stained positive for TGFBR2 and IGF2BP1." (PMID 35639702, 2022). "We found that TGFBR2 and IGF2BP1 were positively stained in 13 (81%) and 10 (62.5%) leiomyoma tissues; however, neither of them was stained in the adjacent myometrium." (PMID 35639702, 2022). "TGFBR2 and IGF2BP1 were positively stained in 81% and 62.5% of leiomyoma tissues but not in adjacent myometrium." (PMID 35639702, 2022).
oral squamous cell carcinoma (4 papers, 2010 to 2020). "The high prevalence of AS in transforming growth factor beta receptor 2 (TGFBR2) has been recently reported in oral squamous cell carcinoma (OSCC) and in potentially malignant oral disorders (PMDs), with almost no such event detected in normal tissues." (PMID 25988147, 2014).
papillary thyroid cancer (4 papers, 2020 to 2022). "We genotyped TGFB1, TGFBR1, and TGFBR2 SNPs in 157 papillary thyroid cancer (PTC) patients and 200 healthy controls." (PMID 33905626, 2021).
prostate tumor (4 papers, 2012 to 2019). "To further understand the cellular changes induced by loss of Tgfbr2 expression in mouse prostate tumors we used transcriptional profiling of these two tumor models." (PMID 29782499, 2018). "Examination of invasive cancers from the Krt8-Cre model did not reveal any overt squamous differentiation, as seen in Apc;Tgfbr2 null mouse prostate tumors, for example." (PMID 29782499, 2018). "To begin to examine how loss of TGFß signaling drives prostate tumor progression we performed transcriptome profiling on normal wild type prostate and on tumors from mice with prostate-specific deletion of Apc, or Pten, with or without deletion of Tgfbr2." (PMID 29782499, 2018). "Here we show that mouse prostate tumors lacking Pten and Tgfbr2 have higher expression of stem cell markers and genes indicative of basal epithelial cells, and that basal cell proliferation is increased compared to Pten mutants." (PMID 29782499, 2018). "No methylation was detected at the TGFBR2 and LDOC1 promoters in prostate tumor samples." (PMID 23185447, 2012).
renal carcinoma (4 papers, 2012 to 2018). A carcinoma arising from the epithelium of the renal parenchyma or the renal pelvis. "In our analysis using The Cancer Genome Atlas data (reported in details below), TGFBR2 was associated with survival in ovarian and renal carcinoma." (PMID 26081588, 2015). "Among these genes specific to Cox-nnet, many have been previously reported to relevant to renal carcinoma development and prognosis, such as CASP9, TGFBR2, KDR (VEGFR)." (PMID 29634719, 2018).
asthma (3 papers, 2016 to 2023). "miR-19a has been found to enhance airway epithelial proliferation as result of the loss of TGFBR2-mediated SMAD3 phosphorylation in ASMCs from patients with severe asthma." (PMID 32714925, 2020). "The expression levels of LRG1 and its receptor transforming growth factor-beta receptor II (TGFBR2) in patients with allergic rhinitis (AR) and asthma (AS) were examined by flow cytometry, and enzyme-linked immunosorbent assay (ELISA)." (PMID 27378305, 2016). "The ligand of TGFBR2, TGF-β, has a well-established role in asthma and airway remodeling, and its receptor was found to be involved in T-cell differentiation." (PMID 36835202, 2023).
atherosclerosis (3 papers, 2021 to 2024). A disease characterized by the build-up of fatty material and calcium deposition in the arterial wall resulting in partial or complete occlusion of the arterial lumen. "Accordingly, endothelial deletion of ALK5 or TGFBR2 in the ApoE−/− atherosclerosis mouse model reduces atherosclerosis plaque burden, plaque collagen content, fibronectin deposition and VCAM-1 expression." (PMID 38323651, 2024).
Cirrhosis (3 papers, 2013 to 2022). A chronic disorder of the liver in which liver tissue becomes scarred and is partially replaced by regenerative nodules and fibrotic tissue resulting in loss of liver function. "In this study, we used immunohistochemical analysis to explore the diagnostic potential of TGFBR1 and TGFBR2 as biomarkers to differentiate HCC from cirrhosis." (PMID 35677836, 2022). "Next, we used multivariable logistic regression to fit a model using H-scores from both TGFBR1 and TGFBR2 scores with HCC versus cirrhosis as the dependent variable." (PMID 35677836, 2022). "We found a significant reduction in TGFBR2 in tissue from patients with HCC compared with tissue from patients with only cirrhosis and that this reduction consistently occurred in regions near tumor tissue in patients with HCC." (PMID 35677836, 2022). "IHC staining intensities for TGFBR1 and TGFBR2 were lower in HCC tissue than in tumor-adjacent tissue (TAT) or in tissue from cirrhosis-only patients." (PMID 35677836, 2022). "HCC tissue also had a significantly reduced TGFBR2 H-score compared to TAT (p = 3.6 ×10−11) or cirrhosis-only tissue (p = 0.028)." (PMID 35677836, 2022). "Based on these results, we tested H- scores for TGFBR1 ranging from 140 to 200 as thresholds for predicting cirrhosis only versus HCC and we tested H-scores ranging from 114 to 145 as TGFBR2 H-score thresholds." (PMID 35677836, 2022). "For TGFBR2, the mean and SD were 105.8 ± 56.9 for HCC tissue (n = 43), 202.3 ± 55.5 for TAT (n = 40), and 145.2 ± 77.5 for cirrhosis-only tissue (n = 28)." (PMID 35677836, 2022). "The mean and SD of the TGFBR2 H-scores were 183.6 ± 69.2 for HCC tissue (n = 11), 227.3 ± 55.6 for TAT (n = 11), and 251.7 ± 38.2 for cirrhosis-only tissue (n = 9)." (PMID 35677836, 2022). "The mean and SD of the AI-assigned H-scores for TGFBR2 were 162.68 ± 63.66 in HCC tissue (n = 62) and 203.44 ± 59.33 in cirrhosis-only tissue (n = 39)." (PMID 35677836, 2022). "Thus, we propose that a reduction in TGFBR2 abundance represents a useful biomarker for detecting HCC in the context of cirrhosis and that incorporating this biomarker into an AI-based automated imaging pipeline could reduce variability in diagnosing HCC from biopsy tissue." (PMID 35677836, 2022). "From these findings, we developed models based on various intensities of TGFBR2 staining and tested their ability diagnostically differentiate HCC from cirrhosis." (PMID 35677836, 2022). "The difference of TGFBR2 staining intensity between HCC tissue and TAT was not significant (p = 0.14) but the difference between HCC tissue and cirrhosis-only tissue was significant (p = 0.018)." (PMID 35677836, 2022).
coronary artery disease (3 papers, 2015 to 2023). "The aim of our study was to assess the association between polymorphisms in the TGF-β1 gene (rs1800469, rs1800470) and in the TGFBR2 gene (rs6785358, rs9838682) and the risk of unstable angina, as well as selected clinical parameters affecting the risk of ischemic heart disease." (PMID 36672663, 2023). "The TGFBR2 gene rs9838682 polymorphism may influence the lipid parameters in patients with coronary artery disease." (PMID 36672663, 2023). "The TGFBR2 gene rs9838682 polymorphism may influence lipid parameters in patients with coronary artery disease." (PMID 36672663, 2023). "A common TGFBR2 polymorphism in a human population was demonstrated to be associated with a risk of sudden cardiac arrest (SCA) due to ventricular arrhythmias (VA) in the setting of coronary artery disease (CAD)." (PMID 35055737, 2022).
depression (3 papers, 2022 to 2025). "Additionally, PAK1 mRNA levels are altered in the prefrontal cortex and hippocampus of depressed subjects, and RT-PCR revealed reduced expression of TGFBR2 in the functional forebrain regions and hippocampus of rodent models of depression." (PMID 39126426, 2024).
diabetic nephropathy (3 papers, 2007 to 2024). "In summary, we investigated if putatively functional variants in three genes, TGFB1, TGFBR1 and TGFBR2, contribute to genetic susceptibility to diabetic nephropathy in type 1 diabetes." (PMID 17319955, 2007). "Variants have been recorded for both TGFBR1 and TGFBR2 genes, however there is limited genomic information regarding their influence on diabetic nephropathy." (PMID 17319955, 2007). "There is considerable evidence supporting the role of TGFB1, TGFBR1 and TGFBR2 genes in the development of diabetic nephropathy." (PMID 17319955, 2007). "The activity of TGFβ1 is facilitated by the action of type 1 and type 2 receptors, with both receptor genes (TGFBR1 and TGFBR2) shown to be upregulated in diabetic kidney disease." (PMID 17319955, 2007). "Analysis of TGFBR2: c.*747C>G genotyping did not reveal a significant association with diabetic nephropathy." (PMID 17319955, 2007). "Our results suggest common variants in TGFB1, TGFBR1 and TGFBR2 genes do not strongly influence genetic susceptibility to diabetic nephropathy in an Irish Caucasian population." (PMID 17319955, 2007). "Genotyping TGFBR2: c.1149G>A did not reveal a significant association with diabetic nephropathy, however we did identify a doubling of the minor allele in cases (MAF: 1.9% in cases vs. 0.8% in controls)." (PMID 17319955, 2007).
glaucoma (3 papers, 2008 to 2024). Increased pressure in the eyeball due to obstruction of the outflow of aqueous humor. "To test the role of TGFβ signaling in glaucoma-relevant phenotypes, we genetically reduced TGFβ signaling using mice with mutated Tgfbr2, which encodes the common receptor for all TGFβ ligands in Col4a1+/G1344D mice." (PMID 38717426, 2024). "–35 Using mice that have reduced levels of TGFBR2, a key receptor of all three TGFβ ligand isoforms, here we examined the role of TGFβ signaling in the context of hallmarks of glaucoma including IOP, optic nerve, and retinal NFL parameters." (PMID 38717426, 2024). "We found that Col4a1+/G1344D mice have multiple pathological hallmarks of glaucoma and that Tgfbr2 heterozygosity partially prevents these phenotypes in Col4a1+/G1344D mice." (PMID 38717426, 2024). "In the current study, using microarray analysis, we identified a number of genes (for example, MYLK, TGFBR2, VCAN, and RAC2) whose expression may underlie higher susceptibility of astrocytes of AA individuals to elevated IOP and that may be relevant to reactive astrocyte responses in glaucoma." (PMID 18613964, 2008).
inflammatory bowel disease (3 papers, 2021 to 2026). A spectrum of small and large bowel inflammatory diseases of unknown etiology. "Heterozygous TGFBR2 loss-of-function mutation is an extremely rare cause of very-early onset inflammatory bowel disease (VEOIBD) as, so far, only three cases have been reported in the literature." (PMID 37168749, 2021).
mitral valve prolapse (3 papers, 2019). A fairly common and often benign valvular heart disorder characterized by redundancy or hooding of mitral valve leaflets so that they prolapse into the left atrium, often causing mitral regurgitation. "The mitral valve prolapse appeared to be significantly influenced by both pathogenic and VUS rare variants in FBN1 and by NOTCH1 and TGFBR2 VUS." (PMID 31536524, 2019). "Valve abnormalities, in particular mitral valve prolapse and insufficiency, affected nearly half of the patients; isolated mitral valve prolapse was also present in seven out of 10 TGFBR2 patients." (PMID 31569402, 2019).
myelofibrosis (3 papers, 2020 to 2024). A partial or complete replacement of the bone marrow stroma by fibrous tissue. "Consistent with this conclusion, we show that genetic abrogation of all TGF-β signaling (by deleting Tgfbr2) in MSCs completely prevented the development of myelofibrosis in the majority of mice in both MPLW515L and Jak2V617F models of MPNs." (PMID 35439167, 2022). "Although requiring experimental validation, we suspect that the low-grade myelofibrosis observed in a minority of Osx-Cre Tgfbr2fl/– recipients is due to inefficient Cre-mediated excision of Tgfbr2." (PMID 35439167, 2022). "This can lead to the hypothesis that myelofibrosis‐derived fibroblasts, acting as cancer‐associated fibroblasts, are highly dependent on TGFBR1, with a possible compensatory down‐regulation of TGFBR2." (PMID 32889753, 2020). "Deletion of Tgfbr2 in osteolineage cells does not affect MPLW515L-induced myelofibrosis." (PMID 35439167, 2022).
nasopharyngeal carcinoma (3 papers, 2014 to 2024). A carcinoma arising from the nasopharyngeal epithelium. "MALAT1 promotes EMT of nasopharyngeal carcinoma cells through de-repressing Capn4 by sponging miR-124 and mediates TGF-β1-induced EndMT by regulating TGFBR2 and SMAD3 through miR-145 in endothelial progenitor cells (EPCs)." (PMID 30871555, 2019).
Nephropathy (3 papers, 2007 to 2025). A nonspecific term referring to disease or damage of the kidneys. "Dysregulation of other factors involved in TGF-β signaling, including BAMBI40, TGFBR2 and TGFBR341 have also been shown to be predisposing factors for the development of nephropathy in diabetic individuals." (PMID 32753679, 2020). "In resequencing the genes we identified eight novel variants for TGFB1, TGFBR1 and TGFBR2 genes but did not detect significant association between any of the common SNPs and nephropathy in this Caucasian population with type 1 diabetes." (PMID 17319955, 2007). "Experimental approaches to TGF-β receptor inhibition in kidney disease include small-molecule kinase inhibitors of ALK5 (TGFBR1) and function-blocking monoclonal antibodies against TGFBR2." (PMID 39990662, 2025). "There are currently no active clinical studies of anti-TGFBR2 monoclonal antibodies for kidney disease." (PMID 39990662, 2025).